PF4 (platelet factor 4)
Diseases named in the same sentence as PF4 in open-access papers (continued):
Sharing a sentence is not in itself a finding about the gene and the disease.
immune thrombocytopenia (28 papers, 2009 to 2026). "PF4-associated immune thrombocytopenia and thrombosis (PITT) has been proposed as a collective name for heparin-induced thrombocytopenia (HIT), VITT, and VITT-like disorders." (PMID 40573981, 2025). "Given the widening spectrum of anti-PF4-mediated TTS, a new collective name for HIT, VITT, and VITT-like disorders has been proposed: PF4-associated immune thrombocytopenia and thrombosis (PITT)." (PMID 40573981, 2025). "Platelet α-granules are rich in transforming growth factor β1 and PF4, which are associated with the functional reprogramming of myeloid-derived suppressor cells in immune thrombocytopenia." (PMID 39736771, 2024). "The WHO’s diagnostic algorithm helped establish a causal link in rare cases of immune thrombocytopenia mediated by platelet factor 4 (PF4) antibodies post-vaccination with ChAdOx1 nCov-19." (PMID 38933672, 2024). "Anti-platelet factor 4 (anti-PF4) antibodies were identified as pathogenic antibodies for vaccine-induced immune thrombocytopenia and thrombosis (VITT) in subjects receiving ChAdOx1 nCoV-19 vaccinations." (PMID 36992276, 2023). "Heparin-induced immune thrombocytopenia is caused by antibodies against complex of heparin and platelet factor 4 (PF4), which can lead to platelet activation and the initiation of thromboses." (PMID 19960059, 2009). "Additionally, the development of other autoantibodies, such as anti-platelet factor 4 (anti-PF4), is related to COVID-associated immune thrombocytopenia." (PMID 38229141, 2024). "The presenting features of VITT may overlap with those of antiphospholipid syndrome associated with anti-PF4 and immune thrombocytopenia." (PMID 36560433, 2022). "This led us to conclude that vaccination with ChAdOx1 nCov-19 may cause the rare development of immune thrombocytopenia mediated by platelet-activating antibodies against platelet factor 4 (PF4), which clinically mimics heparin-induced autoimmune thrombocytopenia." (PMID 34073536, 2021). "Interest in anti-PF4 disorders rekindled when first cases of vaccine-induced immune thrombocytopenia and thrombosis (VITT) occurred during the worldwide COVID-19 vaccination campaign." (PMID 40236285, 2025). "Proposed pathogenetic mechanisms describe a process similar to the autoimmune Heparin Immune Thrombocytopenia (HIT) implicating tetramers of PF4 that crosslink with vaccine proteins to form multimolecular aggregates." (PMID 35246163, 2022). "Increased levels of PF4 and anti-PF4 antibodies are found in patients with Covid-19 and there is a report of a patient who developed immune thrombocytopenia after SARS-CoV-2 infection." (PMID 34290613, 2021). "VITT (vaccine-induced immune thrombocytopenia; another term used VIPIT—vaccine-induced prothrombotic immune thrombocytopenia) was established as a working diagnosis; however, antibodies to the PF4–heparin complex (HIT antibody) were negative." (PMID 36275662, 2022). "Bearing in mind the catastrophic consequences of vaccine-induced immune thrombocytopenia and thrombosis (VITT), our patient was investigated and tested negative for anti-platelet factor 4 (PF4) antibodies." (PMID 36289113, 2022).
viral infection (20 papers, 2013 to 2025). "PF4 is a chemokine abundantly secreted by activated platelets and plays a complex role in various viral infections." (PMID 39772852, 2025). "Platelets, which do not typically interact with neutrophils, become important inducers of NETs in the context of bacterial and viral infections, perhaps mediated by platelet factor-4 (PF4), p-selectin or high-mobility group box 1 (HMBG1)." (PMID 37828990, 2023). "P-selectin and PF-4 are also important markers of platelet activation in other viral infections such as SARS-CoV-2 and HIV." (PMID 36189282, 2022). "Soluble glycosaminoglycans (GAGs) can prevent the tetrameric PF4 from enhancing virus infection, indicating that interacting with cell surface GAGs is required by the tetrameric PF4 to help HIV infection." (PMID 33050376, 2020). "The results indicated that PF4 at different concentrations had similar effects on the viral infection." (PMID 27631372, 2016). "In this study, the results showed that PF4 increased the shrimp phagocytic activity against the virus infection." (PMID 27631372, 2016). "In this study, the results showed that PF4 was involved in the antiviral immune response of shrimp by inhibiting the viral infection in vivo." (PMID 27631372, 2016). "Platelet factor 4 (PF4) has been shown to regulate several viral infections." (PMID 39772852, 2025). "Anti-PF4 antibodies in acute VITT-like disorders can occur after viral infections." (PMID 40236285, 2025). "Others have reported that viral infection of BCs shifts the differentiation trajectory, raising the question of whether chronic Pf4 exposure would have a similar effect." (PMID 38275975, 2024). "These complexes may also boost an immune response against PF4–hexon complexes developed after previous viral infections." (PMID 37834770, 2023). "As VITT-like syndromes are increasingly reported in patients shortly after viral infections, direct virus-PF4 interactions might be most relevant." (PMID 37834770, 2023).
lung fibrosis (19 papers, 2015 to 2025). "Platelet factor 4 (PF4) expression was downregulated in human lung tissue derived from patients diagnosed with pulmonary hypertension secondary to pulmonary fibrosis, but up-regulated in PAH patients." (PMID 27894297, 2016). "This indicates that macrophages may be a potential source of PF4/CXCL4 in mouse models of lung and heart fibrosis, as well as in individuals with pulmonary fibrosis." (PMID 40552264, 2025).
thromboses (18 papers, 2009 to 2025). "Anti-PF4/heparin IgG-negative PV patients encountered thromboses in 43.5%, reflecting a 31% increase in relative thrombotic risk for PV patients with anti-PF4/heparin IgG as compared to IgG-negative PV in our cohort (p > 0.05)." (PMID 28698883, 2017). "Vaccine-induced thrombotic thrombocytopenia (VITT): thrombotic disorder first identified in 2021 as a catastrophic syndrome associated with anti-SARS-CoV-2 adenoviral vector (AdV)-vaccine administration characterized by the presence of anti-PF4 antibodies." (PMID 40573981, 2025). "In patients with chronic recurrent anti-PF4 thromboses, BTK inhibitors may be beneficial, and if caused by a paraprotein, antimyeloma therapy should be considered." (PMID 40236285, 2025). "In addition to the usual diagnostics of thrombophilic risk factors (such as antiphospholipid syndrome), anti-PF4 antibodies should be excluded in a suitable screening assay in all patients with chronic recurrent thromboses." (PMID 40236285, 2025). "Platelets are also able to bind such complexes via their FcgammRIIA receptor, resulting in the activation and release of PF4, aggregation of platelets, and resulting thromboses." (PMID 34639132, 2021). "The thrombotic disease/inflammation progress-related protein PF4 and sFRP1, a member of the Wnt/fz signal-transduction pathway and related to myocardial repair, are significantly up-regulated in triple-vessel disease with/without left main stenosis." (PMID 28947991, 2017). "Further insight into the functional basis of this phenomenon could inform measures to reduce anti-PF4/heparin antibody formation and potential thromboses." (PMID 28698883, 2017). "Platelet factor 4 (PF4) is stored in platelet (PLT) granules and was identified as an important player in thrombotic diseases in previous studies." (PMID 35869501, 2022). "There is growing evidence that anti-PF4 antibodies can lead to severe thrombotic disorders not only in the absence of heparin treatment but also in the administration of anti-SARS-CoV-2 AdV vaccines." (PMID 40573981, 2025).
liver fibrosis (17 papers, 2006 to 2024). "They suggested that similar to AMKL myelofibrosis, abnormal blasts in TAM proliferate in the liver during the fetal period, producing excessive cytokines, including TGF-β1, PDGF, and PF4, which stimulate growth and collagen synthesis in fibroblasts to cause liver fibrosis." (PMID 39281382, 2024). "Platelet factor 4 (PF4) is a pleiotropic inflammatory chemokine, which has been implicated in various inflammatory disorders including liver fibrosis." (PMID 30971954, 2019). "Notably, PF4 has already been designated as an inflammatory mediator in atherosclerosis and liver fibrosis." (PMID 30971954, 2019). "PF4 could also be involved in the modulation of liver fibrosis, since its genetic deletion in CCl4-induced murine liver fibrosis, reduced histological liver damage and fibrosis-related transcript levels, and resulted in the reduction of immune cell infiltration in the liver." (PMID 38116017, 2023). "Thus, unlike in liver fibrosis and other murine models of inflammation, where PF4-mediated neutrophil recruitment plays an important pathogenic role, PF4-driven hepatic neutrophil infiltration does not appear to contribute to GalN/LPS-induced liver injury." (PMID 30971954, 2019).
diabetes (16 papers, 2013 to 2025). "Gender, duration of diabetes mellitus, hip measurement, treatment with aspirin, HbA1c level, fibrinogen, triglycerides, glucose concentration and glucose concentration squared, PF4 and CD40L were associated with t50%." (PMID 25928628, 2015). "With diabetes as an independent risk factor, the positivity rate of the anti-PF4/heparin antibody decreased in the patients undergoing weekly dialyses ≥3 times." (PMID 23646121, 2013). "PF4 could be associated with vascular disturbance in the early stages of diabetes, but this effect disappears after longer exposure to the diabetic microenvironment." (PMID 38331889, 2024). "Diabetes is associated with the development of EC dysfunction, enhanced platelet aggregation and activation, increased circulating platelet aggregates, and a higher level of platelet release products, such as beta-thromboglobulin, thromboxane B2, and PF4." (PMID 24672719, 2014). "The purpose of this study was to identify whether diabetes increased the likelihood of heparin-induced platelet factor 4 antibodies in at risk vascular patients.Methods." (PMID 24672719, 2014). "The univariate analysis revealed that the positivity rate of the serum anti-PF4/heparin antibody was significantly increased in the MHD patients whose primary diseases were diabetes and elevated diastolic blood pressures (DBPs)." (PMID 23646121, 2013). "The current study reports that PF4 was significantly reduced in MPs of patients with diabetes without CAD and those with ACS, but not CCAD." (PMID 35109843, 2022). "PF4 was significantly reduced in patients with diabetes without versus those with ACS (92.800 ± 26.1, 79.000 ± 50.3 respectively, p < 0.05), but not with CCAD (90.700 ± 41.8)." (PMID 35109843, 2022). "Moreover, studies have suggested that PF4 levels are elevated in DKD, with PF4 levels in insulin-dependent patients with diabetes with substantial albuminuria being significantly elevated compared to those in patients with diabetes with mild albuminuria and healthy controls." (PMID 37834171, 2023).
malaria (16 papers, 2010 to 2024). Malaria is a serious and sometimes fatal disease caused by a parasite that commonly infects a certain type of mosquito which feeds on humans. "Beyond malaria, in vitro and mouse model studies on vascular permeability, leukocyte recruitment, and endothelial cell signaling have shown PF4 to cause increased endothelial permeability in response to cellular damage." (PMID 38693577, 2024). "Here, we show for the first time in humans the clinical characteristics by which platelet-associated PF4 aids in the suppression of intra-erythrocytic malaria parasites, a circulating microbial pathogen." (PMID 37310126, 2023). "Thus, CICs could mediate pathogenic processes of anti-PF4/P immune complexes in patients with malaria through engagement of Fc receptors, such as FcγRIIA, or through opsonization." (PMID 38652559, 2024). "CIC levels were substantially elevated in approximately 75% of malaria cases tested here and positively correlated with anti-PF4/P, as well as with MPO, parasite cfDNA, sST2, and sCD62p in Ret+ CM." (PMID 38652559, 2024). "In-depth immunophenotyping of autoantibody-secreting B cells will be necessary to understand anti-PF4/P and anti-PS antibody production in pediatric malaria patients." (PMID 38652559, 2024). "In in vitro malaria studies, PF4 has been shown to play a protective role in platelet-mediated killing of Pf-iRBCs." (PMID 38693577, 2024). "To better understand how sST2 and sCD40L plasma levels relate to anti–PF4/P IgG levels in CM, we plotted the values in relation to the following malaria case classifications: UM, Ret+ CM survival, or fatal Ret+ CM." (PMID 38652559, 2024). "Platelet-derived antimicrobial molecules have the broad-spectrum activities against pathogens, and platelet factor 4 (PF4) is the first platelet-derived host defence peptide discovered as killing the malaria parasite." (PMID 37310126, 2023). "In contrast, another recent study examining the blood of naturally infected malaria patients demonstrated an intraerythrocytic accumulation of PF4 leading to parasite elimination as well as a platelet-dependent reduction of parasite growth in vitro." (PMID 30483508, 2018). "For instance, platelet released PF4 was proven to bind red blood cells infected with the malaria parasite Plasmodium falciparum and helps to eliminate the intracellular parasite." (PMID 30483508, 2018). "Apart from its role in malaria, PF4 binds to a variety of bacterial strains thereby exposing them as a target of anti-PF4-antibodies, which leads to an enhanced phagocytosis by immune cells." (PMID 30483508, 2018). "In some patients with malaria, anti-PF4/P IgG levels were elevated above the assay clinical cutoff point (OD = 0.4) for HIT diagnosis, with a higher proportion of levels above the cutoff point observed in patients with CM relative to those with UM (27% of CM vs. 1.6% of UM)." (PMID 38652559, 2024). "Induction of autoantibodies, such anti-PF4/P, in a subset of patients with malaria may be one of multiple mechanisms that tilts a UM case toward CM." (PMID 38652559, 2024). "As with malaria, PF4 is also central to effective E. coli killing." (PMID 31572400, 2019). "One explanation for the finding of reduced odds of severe malaria in patients with FYB carriage could be that it affects binding affinity towards PF4 and thereby the capacity of platelet mediated killing." (PMID 31551092, 2019). "During acute P. falciparum infection in humans plasma concentrations of PF4 are also elevated and we have shown that plasma PF4 is greatly increased in ECM (over 1 μg/mL), demonstrating a potentially significant role for platelets and PF4 in mediating malaria associated immune dysregulation." (PMID 20454664, 2010). "The present study has identified two genes PF3D7_1233400 and PF3D7_1437500 containing peptide fragment (PF4-123 and PF4-143) with B-cell epitopes that are correlated with naturally acquired immunity to malaria." (PMID 27207101, 2016).
malaria (continued). "Despite the decrease in PF4/CXCL4 found in our PLT proteomes from P. vivax patients, we did not detect increased plasma levels of this chemokine in our patients compared to healthy donors; however, high variability was observed within the malaria group." (PMID 34991449, 2022). "Compared with healthy pediatric community controls and sick comatose children (NMC controls) infected with non-Plasmodium infectious agents, anti–PF4 IgG levels were elevated in patients with malaria (UM and CM), suggesting that anti-PF4/P antibody production may be specific to Plasmodium infection." (PMID 38652559, 2024). "Also, clinical evidence has demonstrated that plasma PF4/CXCL4 is a predictive biomarker of cerebral malaria in humans, while other studies suggested this protein is not important in malaria pathogenesis." (PMID 34991449, 2022).
Arterial thrombosis (15 papers, 2020 to 2026). The formation of a blood clot inside an artery. "More rarely, immunothrombosis has been described due to heparin-induced thrombocytopenia (HIT); this is an immune complication of heparin therapy caused by pathological anti-platelet factor 4 (PF4)/heparin antibodies often causing venous or arterial thrombosis." (PMID 37771078, 2024). "It is reasonable to assume that these specific mechanisms, driven by anti-β2-GPI/PF4, converge to create a pro-thrombotic state, which can manifest with arterial thrombosis." (PMID 41601650, 2026). "Consequently, thrombus formation on collagen under flow conditions was reduced ex vivo, and Grin1fl/fl-Pf4-Cre+ mice were protected against arterial thrombosis." (PMID 37252113, 2023). "Therefore, we analyzed Grin1fl/fl-Pf4-Cre+ and Grin1fl/fl-Pf4-Cre− mice in two different mouse models of arterial thrombosis." (PMID 37252113, 2023). "Less commonly, arterial thrombosis may occur, and ELISA confirms positive PF4 “HIT” (heparin-induced thrombocytopenia)." (PMID 36300183, 2022). "DVT, PE, arterial thrombosis, and hospital death each occurred more frequently in PF4-positive versus PF4-negative patients." (PMID 37907435, 2023). "Although none of our patients had a venous or arterial thrombosis, the overall mortality in 20 patients with positive anti-PF4/heparin antibodies was found to be 45%." (PMID 33306320, 2020). "Nevertheless, bright fluorescence and thus identification of platelets in mT/mG;PF4-Cre positive and negative mice could be observed that allows tracing of platelets not only ex vivo but also in vivo to analyze arterial thrombosis without additional labeling of platelets by a fluorescent dye." (PMID 33918229, 2021).